IL3RA (interleukin 3 receptor subunit alpha)
Description:
Cell surface receptor for IL3 expressed on hematopoietic progenitor cells, monocytes and B-lymphocytes that controls the production and differentiation of hematopoietic progenitor cells into lineage-restricted cells. Ligand stimulation rapidly induces hetrodimerization with IL3RB, phosphorylation and enzyme activity of effector proteins such as JAK2 and PI3K that play a role in signaling cell proliferation and differentiation. Activation of JAK2 leads to STAT5-mediated transcriptional program (By similarity).
Synonyms: IL-3R-alpha; CD123; IL3R; IL3RAY; IL3RX; IL3RY; hIL-3Ra
Tractability: Small molecule: a structure with a bound ligand is known. Antibody: a drug acting on it is in phase 2 or 3 trials; UniProt places it where antibodies can reach, with high confidence; its Gene Ontology location is reachable by antibodies, with high confidence; UniProt predicts a signal peptide or a membrane-spanning region. PROTAC: UniProt records ubiquitination sites on it. Other modalities: an approved drug acts on it.
Target class: Membrane receptor
Gene: Protein-coding gene on chromosome X (1,335,025 to 1,382,689, forward strand). Ensembl gene ENSG00000185291.
Subcellular location: Cell membrane
Pathways (Reactome):
Immune System: Interleukin receptor SHC signaling; Interleukin-3, Interleukin-5 and GM-CSF signaling
Signal Transduction: RAF/MAP kinase cascade
Gene Ontology:
Molecular function: interleukin-3 receptor activity; protein binding; cytokine binding; cytokine receptor activity
Biological process: interleukin-3-mediated signaling pathway; cytokine-mediated signaling pathway; positive regulation of cell population proliferation; cellular response to interleukin-3
Cellular component: plasma membrane; external side of plasma membrane; interleukin-3 receptor complex; receptor complex; membrane
Homologues: Orthologues: macaque IL3RA (87% identical), dog IL3RA (44% identical), rat Il3ra (30% identical), zebrafish il2rgb (15% identical), zebrafish il2rga (13% identical), zebrafish lifra (12% identical), zebrafish lifrb (12% identical), zebrafish il6r (11% identical), tropical clawed frog il2rg (11% identical), zebrafish il11ra (10% identical), zebrafish ghra (10% identical), zebrafish ghrb (9% identical), and 1 more. Paralogues in human: IL13RA1 (19% identical), LIFR (14% identical), PRLR (14% identical), CSF2RA (13% identical), LEPR (13% identical), CSF3R (13% identical), IL6ST (12% identical), OSMR (12% identical), GHR (11% identical), IL12RB2 (11% identical), CRLF1 (11% identical), IL31RA (11% identical), and 11 more.
Diseases named in the same sentence as IL3RA in open-access papers:
IL3RA is named in the same sentence as 53 diseases in open-access papers, as found by Europe PMC text mining. Sharing a sentence is not in itself a finding about the gene and the disease. The quoted sentences say what the papers report.
leukemia (7 papers, 2017 to 2024). A malignant (clonal) hematologic disorder, involving hematopoietic stem cells and characterized by the presence of primitive or atypical myeloid or lymphoid cells in the bone marrow and the blood. "Because RUNX1 is commonly mutated in AML, it is possible that RUNX1 loss contributes to leukemia pathogenesis by increasing IL-3RA expression." (PMID 37581927, 2023). "IL-3RA has also been described as a marker for leukemia stem cells, which are associated with chemoresistance and disease relapse." (PMID 37581927, 2023). "The current study found that IL3RA has considerable significance in the prognostic risk model of leukemia, while PIK3CA in breast cancer." (PMID 35769153, 2022). "This revealed binding of MYB::PLEKHO1 to the transcription start sites of BPDCN-associated genes such as Il3ra (CD123), Bcl2, and Myc, which were strongly expressed in leukemia cells." (PMID 39499902, 2024). "The level of expression of IL3RA correlates significantly with the number of leukemia blasts at the time of diagnosis." (PMID 35769153, 2022). "There is a significant correlation between the level of IL3RA expression and the number of blasts at the time of leukemia diagnosis." (PMID 35769153, 2022). "In the CD34+CD38–TIM3+CD99+ leukemia stem cell–enriched (LSC-enriched) fraction, RUNX1mut LSCs (SU371) exhibited higher expression of IL-3RA compared with matched RUNX1wt LSCs (SU524, SU770)." (PMID 37581927, 2023). "Conditional knockdown of IL3RA in EP300-ZF384-positive cells inhibited the proliferation in vitro, and induced a significant increase in overall survival of mice, which is attributed to impaired propagation ability of leukemia cells." (PMID 38566191, 2024). "The antitumor efficacy of the IL3RA-ADC BAY-943 was tested in two IL3RA-positive, systemic (intravenous transplantation) cell line-derived xenografts: MOLM-13 human AML and MV-4-11 human biphenotypic leukemia models in mice." (PMID 33233768, 2020). "By contrast, in the MOLM-13 model, 80–100% of the mice treated with 10 mg/kg IL3RA-ADC survived without signs of leukemia until day 123, when the study was terminated, while all mice treated with the isotype control ADC were sacrificed due to signs of disease by day 67 after tumor cell inoculation." (PMID 33233768, 2020). "Interleukin-3 receptor subunit alpha or CD123 is very frequently expressed on both blast and leukemic progenitor cell populations in AML as well as in B-ALL and other rare leukemia subtypes, but not in T-ALL." (PMID 30897713, 2019). "Several genes upregulated in the TF1a dormancy model have been described in leukaemia initiating cells, but appear not to be crucial for maintenance of normal HSCs, e.g. CD44, ITGB3, TIM3 (HAVCR2) and IL3RA." (PMID 29340063, 2017).
acute myeloid leukemia (6 papers, 2017 to 2024). Acute myeloid leukemia (AML) is a group of neoplasms arising from precursor cells committed to the myeloid cell-line differentiation. "IL3RA (alpha subunit of the interleukin 3 receptor) is a cell membrane protein frequently expressed in acute myeloid leukemia (AML) and Hodgkin lymphoma; therefore, it is a promising therapeutic target for cancer treatment." (PMID 33233768, 2020). "IL3RA is expressed at high levels in ≈80% of acute myeloid leukemias (AML), 59–100% of classical Hodgkin lymphomas (cHL), and the majority of blastic plasmacytoid dendritic cell neoplasms (BPDCN)." (PMID 33233768, 2020). "IL3RA is frequently expressed in acute myeloid leukemia (AML) and classical Hodgkin lymphoma (HL), presenting an opportunity to treat AML and HL with an IL3RA-directed antibody–drug conjugate (ADC)." (PMID 33233768, 2020).
COVID-19 (4 papers, 2021 to 2025). A disease caused by infection with severe acute respiratory syndrome coronavirus 2. "Two of them are negatively associated with the risk of severe COVID-19, including interleukin-3-receptor subunit alpha (OR per SD increment: 0.87, 95% CI: 0.79–0.94) and prostate-associated microseminoprotein (OR: 0.71, 95% CI: 0.58–0.86)." (PMID 35602208, 2021). "Six proteins showed sex differences in levels over time, of which 3 were also associated with severe COVID-19: CCL26, IL1RL2, and IL3RA, providing insights to better understand the marked differences in outcomes by sex." (PMID 36171541, 2022). "Mendelian randomization results are consistent with a direct link between the plasma levels of a closely related cytokine receptor subunit, IL3RA, and critical COVID-19." (PMID 35255492, 2022). "However, our observations on TLR5, CXCL17, CCL26, IL1RL2, and IL3RA provide clear proteins to explore to explain sex differences in COVID-19 outcomes." (PMID 36171541, 2022).
autoimmune disease (3 papers, 2016 to 2025). A disorder resulting from loss of function or tissue destruction of an organ or multiple organs, arising from humoral or cellular immune responses of the individual to their own tissue constituents. "IL3RA was speculated to be linked to the increased risk of autoimmune diseases in Turner syndrome in many studies." (PMID 36733527, 2023).
breast carcinoma (3 papers, 2022 to 2025). "Six of the genes (CASP1, CCL2, ADGRE5, IL3RA, RSPO1, and STAB1) are co‐expressed with the CH25H gene in both cancers, while two genes (ANPEP in breast cancer and CCL8 in prostate cancer) are exclusively co‐expressed with the CH25H gene in one of the tumors." (PMID 41159143, 2025).
Hodgkins lymphoma (2 papers, 2020 to 2022). A heterogeneous group of malignant lymphoid neoplasms of B-cell origin characterized histologically by the presence of Hodgkin and Reed-Sternberg (HRS) cells in the vast majority of cases. "In the IL3RA-positive HDLM-2 subcutaneous Hodgkin lymphoma model, IL3RA-ADC treatment also resulted in significant antitumor efficacy with most animals being tumor-free at the end of the study." (PMID 33233768, 2020). "Here, we introduce BAY-943, a novel IL3RA-targeting antibody–drug conjugate that shows potent and selective efficacy in IL3RA-positive AML and Hodgkin lymphoma cell lines." (PMID 33233768, 2020). "The novel IL3RA-ADC with a differentiated mode-of action demonstrates selective binding and internalization to IL3RA-positive cells, which translates into selective and efficacious antitumor activity in IL3RA-positive AML and Hodgkin lymphoma models." (PMID 33233768, 2020).
osteoarthritis (2 papers, 2019 to 2024). A noninflammatory degenerative joint disease occurring chiefly in older persons, characterized by degeneration of the articular cartilage, hypertrophy of bone at the margins and changes in the synovial membrane. "However, IL3, a specific ligand of IL3RA, plays a chondroprotective role in osteoarthritis (OA), a degenerative disease of joints." (PMID 39456698, 2024).
schizophrenia (2 papers, 2012 to 2014). A major psychotic disorder characterized by abnormalities in the perception or expression of reality. "IL3 receptors, including IL3RA and CSF2RB (or IL3RB), were also found significantly associated with schizophrenia in three different populations." (PMID 23226269, 2012).
Alzheimer disease (1 paper, 2021). A progressive, neurodegenerative disease characterized by loss of function and death of nerve cells in several areas of the brain leading to loss of cognitive function such as memory and language. "In summary, this study we have also identified important genes (NRG1, NEDD9, IRF5, IFI35, STAT1, STAT2, JAK2, IL3RA), and alterations in biological processes and pathways that may be associated with Alzheimer’s Disease." (PMID 34484988, 2021).
atherosclerosis (1 paper, 2017). A disease characterized by the build-up of fatty material and calcium deposition in the arterial wall resulting in partial or complete occlusion of the arterial lumen. "Furthermore, other upregulated genes were those of the pro-inflammatory interleukins IL3RA, IL7R, IL8, IL11, usually secreted by immune system cells, and of the NF-κB family (NF-κBIA, NF-κBIZ, NF-κBIE), nuclear transcription factors known to be involved in the development of atherosclerosis." (PMID 28224128, 2017).
breast tumor (1 paper, 2022). "IL-3 and GM-CSF receptor genes (IL3RA, CSF2RA, and CSF2RB) were expressed in human normal mammary epithelial and breast tumor cells at markedly higher levels compared with TSLP receptor (CRLF2)." (PMID 35657353, 2022).
disc degeneration (1 paper, 2024). "Although our study provided in vitro evidence of IL3RA function, whether the same cascade of inflammatory mediators and the protective effects of IL3RA on collagen content are present in different forms of disc degeneration in vivo requires further investigation." (PMID 39456698, 2024).
glioma (1 paper, 2024). A benign or malignant brain and spinal cord tumor that arises from glial cells (astrocytes, oligodendrocytes, ependymal cells). "CLIC4 expression levels were positively correlated with specific markers of macrophages (CD80, CD86, MRC1), neutrophils (FCGR3A, FCGR3B), eosinophils (SIGLEC8, IL3RA), T cells (CD3D, CD4), CD8+ T cells (CD8A, CD8D), NK cells (NCAM1), and B cells (CD19) in glioma." (PMID 39595145, 2024).
liver toxicity (1 paper, 2020). "IL3RA-ADC was well-tolerated without adverse events typically observed with ADCs containing other payload classes, such as thrombocytopenia, neutropenia, or signs of liver toxicity." (PMID 33233768, 2020).
lung carcinoma (1 paper, 2026). "RESULTS: Eight PANoptosis-related genes (DAPK2, CAV1, PDK4, IL3RA, NOTCH1, CHMP4B, IRAK1, and SFN) were identified as being significantly associated with lung cancer." (PMID 41760846, 2026).
malaria (1 paper, 2022). Malaria is a serious and sometimes fatal disease caused by a parasite that commonly infects a certain type of mosquito which feeds on humans. "Among the top 50 genes identified in our RNA-Seq experiment, 5 of them (IFNG, CXCL8, IL3RA, SNX10, MYOF, and RSAD2) had promoter regions that were significantly more accessible in convalescent child patients with malaria than in adult convalescent patients." (PMID 35642634, 2022).
melanoma (1 paper, 2024). A malignant, usually aggressive tumor composed of atypical, neoplastic melanocytes. "The X‐linked cancer‐related genes that have been associated with melanoma include ZNF280C, IL3RA, PNMA3, NHS, and FGD1." (PMID 38827026, 2024).
myeloid leukemia (1 paper, 2024). A clonal proliferation of myeloid cells and their precursors in the bone marrow, peripheral blood, and spleen. "Similar results were also observed in BALL-1, Daudi, and KG-1α cells with EP300-ZNF384, supporting that EP300-ZNF384 fusion protein promotes the expression of IL3RA in both B and myeloid leukemia cell lines." (PMID 38566191, 2024).
myeloma (1 paper, 2024). "They discovered that co-culturing pDCs with myeloma cells increases CD73, CD274, HDAC6, TLR7/9, or IL3Ra/CD123 gene expression, while reducing the expression of ADAM33, BAD, BAK1, and CASP3 in tumor cells." (PMID 39087026, 2024).
neutropenia (1 paper, 2020). A decrease in the number of neutrophils found in the blood. "Importantly, liver toxicity, thrombocytopenia, and neutropenia, which are frequently observed with ADCs in the clinic and in cynomolgus monkey preclinical studies, were not apparent, which was most likely due to the fact that the IL3RA-ADC toxophore metabolite is non-cell permeable." (PMID 33233768, 2020).
Obesity (1 paper, 2025). Accumulation of substantial excess body fat. "Sex-differential disease-related genes include those associated with obesity (PPARG, INSR), cancer (FGFR1, CD22), and immunity (IL6R, IL3RA)." (PMID 40707586, 2025).
oropharyngeal cancers (1 paper, 2018). Carcinoma, predominantly squamous cell, arising from the epithelial cells of the oropharynx. "Interestingly, IL3RA, HLA-A and HLA-B have copy number gains in HPV positive oropharyngeal cancers." (PMID 29879932, 2018).
pancreatic cancer (1 paper, 2023). "These genes were overlapped with 9,170 DEGs in PAAD, which were obtained by comparing the mRNA expression profile between pancreatic cancer in TCGA and the normal pancreas in GTEx; six specific genes were found, including VWF, GNG11, FGF7, TNXB, IL3RA, and LPAR1." (PMID 37070074, 2023).
pancreatic ductal adenocarcinoma (1 paper, 2023). An infiltrating adenocarcinoma that arises from the epithelial cells of the pancreas. "High levels of IL3RA were found in pancreatic ductal adenocarcinoma patients with improved survival." (PMID 37070074, 2023).
psoriasis (1 paper, 2018). An autoimmune condition characterized by red, well-delineated plaques with silvery scales that are usually on the extensor surfaces and scalp. "We therefore investigated whether pDCs are present in paradoxical psoriasis skin lesions by staining paraffin-embedded sections with CD123 (IL3RA)." (PMID 29295985, 2018).
sarcoidosis (1 paper, 2025). Sarcoidosis is a multisystemic disorder of unknown cause characterized by the formation of immune granulomas in involved organs. "A heatmap analysis further demonstrated an upregulation of key genes involved in these pathways, particularly in the progressive sarcoidosis group, including CSF2RB, CSF2RA, IL3RA, STAT5A, and STAT1." (PMID 41476976, 2025).
spinal disease (1 paper, 2024). "We suspected that the mutation in IL3RA was the main cause of spinal disease in this family for various reasons." (PMID 39456698, 2024). "There is no direct evidence that IL3RA contributes to spinal diseases." (PMID 39456698, 2024).
triple-negative breast carcinoma (1 paper, 2022). An invasive breast carcinoma which is negative for expression of estrogen receptor (ER), progesterone receptor (PR), and human epidermal growth factor receptor 2 (HER2). "Tatiana lopatina found IL3RA Inhibition of metastatic spread of triple-negative breast cancer by extracellular vesicle reprogramming." (PMID 35769153, 2022).